UNC13A (unc-13 homolog A)
Description:
Plays a role in vesicle maturation during exocytosis as a target of the diacylglycerol second messenger pathway. Involved in neurotransmitter release by acting in synaptic vesicle priming prior to vesicle fusion and participates in the activity-dependent refilling of readily releasable vesicle pool (RRP). Essential for synaptic vesicle maturation in most excitatory/glutamatergic but not inhibitory/GABA-mediated synapses. Facilitates neuronal dense core vesicles fusion as well as controls the location and efficiency of their synaptic release (By similarity). Also involved in secretory granule priming in insulin secretion. Plays a role in dendrite formation by melanocytes.
Synonyms: KIAA1032; Munc13-1; IDDSF; NEDHES; NEDSMS
Tractability: Antibody: UniProt places it where antibodies can reach, with medium confidence; its Gene Ontology location is reachable by antibodies, with medium confidence. PROTAC: ubiquitination databases record sites on it; its protein half-life has been measured.
Gene: Protein-coding gene on chromosome 19 (17,601,336 to 17,688,365, reverse strand). Ensembl gene ENSG00000130477.
Subcellular location: Cytoplasm; Cell membrane; Presynaptic cell membrane; Presynaptic active zone
Gene Ontology:
Molecular function: calmodulin binding; syntaxin-1 binding; calcium ion binding; diacylglycerol binding; phospholipid binding
Biological process: positive regulation of dendrite extension; dense core granule priming; neuronal dense core vesicle exocytosis; neurotransmitter secretion; regulation of synaptic transmission, glutamatergic; synaptic transmission, glutamatergic; synaptic vesicle priming; chemical synaptic transmission
Cellular component: cytoplasm; neuromuscular junction; neuron projection; plasma membrane; presynaptic active zone; presynaptic membrane; synaptic vesicle membrane; terminal bouton
Genetic constraint (gnomAD): Loss-of-function variants: 61 observed, 193.99 expected, observed/expected ratio (o/e) 0.31, 90% interval 0.25 to 0.39. The upper end of that interval is the gene's LOEUF score, 0.39, which puts it in group 1 of 6, group 1 being the genes least tolerant of losing a copy. Missense variants: 1,452 observed, 2,106.4 expected, observed/expected ratio (o/e) 0.69, 90% interval 0.66 to 0.72. Synonymous variants: 906 observed, 830.87 expected, observed/expected ratio (o/e) 1.09, 90% interval 1.03 to 1.15.
Homologues: Orthologues: macaque UNC13A (98% identical), dog UNC13A (98% identical), mouse Unc13a (96% identical), rat Unc13a (96% identical), chimpanzee UNC13A (95% identical), guinea pig UNC13A (89% identical), zebrafish unc13a (82% identical). Paralogues in human: UNC13B (73% identical), UNC13C (58% identical).
Diseases named in the same sentence as UNC13A in open-access papers:
UNC13A is named in the same sentence as 50 diseases in open-access papers, as found by Europe PMC text mining. Sharing a sentence is not in itself a finding about the gene and the disease. The quoted sentences say what the papers report.
amyotrophic lateral sclerosis (19 papers, 2013 to 2026). Amyotrophic lateral sclerosis (ALS) is a neurodegenerative disease characterized by progressive muscular paralysis reflecting degeneration of motor neurons in the primary motor cortex, corticospinal tracts, brainstem and spinal cord. "UNC13A (rs12608932‐CC) is associated with both amyotrophic lateral sclerosis (ALS) and frontotemporal dementia (FTD), and shortens survival in ALS." (PMID 40214138, 2025). "Another SLE up-DPpGC is UNC13A, a common risk locus for both amyotrophic lateral sclerosis and immune disorders." (PMID 37048133, 2023). "The UNC13A gene is an established susceptibility locus for amyotrophic lateral sclerosis (ALS) and a determinant of shorter survival after disease onset, with up to 33.0 months difference in life expectancy for carriers of the rs12608932 risk genotype." (PMID 36819716, 2023). "This study shows that TDP-43 is the most important repressor of cryptic exon splicing in UNC13A, a risk factor for amyotrophic lateral sclerosis and frontotemporal dementia." (PMID 36930682, 2023). "Two common intronic UNC13A polymorphisms strongly associated with amyotrophic lateral sclerosis and frontotemporal dementia risk overlap with TDP-43 binding sites." (PMID 35197628, 2022). "TDP-43 controls an exon splicing event in UNC13A that results in the inclusion of a cryptic exon associated with frontotemporal dementia and amyotrophic lateral sclerosis." (PMID 35197626, 2022). "Variants of UNC13A, a critical gene for synapse function, increase the risk of amyotrophic lateral sclerosis and frontotemporal dementia, two related neurodegenerative diseases defined by mislocalization of the RNA-binding protein TDP-434,5." (PMID 35197628, 2022). "TDP-43 nuclear depletion in amyotrophic lateral sclerosis (ALS) causes de-repression of cryptic exons (CEs) in multiple transcripts, including UNC13A and STMN2, disrupting synaptic transmission and neurite outgrowth." (PMID 41394711, 2025). "One of these cryptic exons is in UNC13A, a genetic risk factor for amyotrophic lateral sclerosis (ALS) and frontotemporal dementia (FTD)." (PMID 36930682, 2023). "In humans, specific variants of the genes UNC13A and UNC13B are associated with the severe degenerative motoneuron disease amyotrophic lateral sclerosis (ALS), as well as with bipolar affective disorder." (PMID 41399760, 2026). "A recent study has shown that single nucleotide polymorphisms in UNC13A (unc-13 homolog A) gene may be associated with sporadic amyotrophic lateral sclerosis (ALS)." (PMID 24688734, 2013). "Recently, the UNC13A gene has been identified as a survival modifier in patients with sporadic Amyotrophic lateral sclerosis (ALS) and Frontotemporal dementia." (PMID 41028013, 2025). "A lack of the UNC13A protein impairs synapse function and underlies the pathological mechanism of neurodegenerative diseases including amyotrophic lateral sclerosis (ALS) and frontotemporal dementia (FTD)." (PMID 39858525, 2025).
frontotemporal dementia (14 papers, 2017 to 2025). Frontotemporal dementia (FTD) comprises a group of neurodegenerative disorders, characterized by progressive changes in behavior, executive dysfunction and language impairment, as a result of degeneration of the medial prefrontal and frontoinsular cortices. "It is a prominent candidate gene for ALS, with UNC13A SNPs being significant genetic markers associated with both frontotemporal dementia (FTD) and ALS in genome-wide association studies." (PMID 40170896, 2025). "Our results are consistent with previous findings demonstrating that UNC13A plays a critical role in ALS and frontotemporal dementia, where genetic variants together with TDP-43 loss of function lead to aberrant splicing, including the insertion of a cryptic exon." (PMID 40879740, 2025). "Furthermore, single nucleotide polymorphisms (SNPs) in UNC13A (associated with increased ALS and frontotemporal dementia (FTD) risk through genome-wide association studies) were found to promote this incorrect splicing in patient brain tissues." (PMID 36575535, 2022). "Also in brain samples of patients affected by frontotemporal lobar degeneration with TDP-43 proteinopathy (FTLD-TDP) the inclusion of the UNC13A cryptic exon was observed together with reduced UNC13A protein level." (PMID 36819716, 2023).
developmental delay (7 papers, 2019 to 2025). "Two patients harboring homozygous truncating variants in UNC13A showed profound developmental delay and died during early childhood." (PMID 41125872, 2025). "The PL mutation, identified in the human UNC13A, has been associated with a dyskinetic movement disorder, developmental delay, and autism." (PMID 40215098, 2025). "A patient with developmental delay, dyskinetic movement disorder and autism has been previously identified with a de novo variant in the UNC13A gene." (PMID 37543562, 2023). "Moreover, gain-of-function variants in RPH3A and UNC13A have been detected in individuals with phenotypes ranging from epilepsy and developmental delay to ASD." (PMID 40649845, 2025). "Unc13a, a neurotransmitter release regulator at nerve cell synapses, single-nucleotide exchange in the Unc13a gene, was reported in a number of disorders including delayed cognitive development, speech impairment, ASD, and ADHD." (PMID 31652960, 2019). "In contrast to UNC13A-CMS caused by biallelic truncation variants, hemiallelic pathogenic missense variants of UNC13A do not cause CMS but cause dyskinesia, developmental delay, and autism." (PMID 36835142, 2023).
autism (5 papers, 2020 to 2025). Persistent deficits in social interaction and communication and interaction as well as a markedly restricted repertoire of activity and interest as well as repetitive patterns of behavior. "A new heterozygous mutation of Unc13a was reported in a patient with dyskinesia, cognitive retardation, speech disorder, autism and hyperactivity." (PMID 32392183, 2020).
epilepsy (5 papers, 2019 to 2025). A brain disorder characterized by episodes of abnormally increased neuronal discharge resulting in transient episodes of sensory or motor neurological dysfunction, or psychic dysfunction. "Although UNC13A variants have been reported to be associated with various neurological disorders, their involvement in epilepsy remains uncertain." (PMID 39634123, 2025). "This further supports the pathogenicity of UNC13A variants in epilepsy." (PMID 39634123, 2025). "Taken together, our experimental results from knocking out, knocking down, and overexpressing variants of UNC13A indicate that dysfunction of this gene could give rise to epilepsy phenotypes." (PMID 39634123, 2025). "In contrast, two UNC13A patients presented with refractory epilepsy, failing to achieve seizure control despite treatment with multiple anti-seizure medications." (PMID 39634123, 2025). "To investigate the role of UNC13A in the pathogenesis of epilepsy, we first examined its function using CRISPR/Cas9 mutagenesis in an F0 zebrafish model, which has been established as a rapid and reliable system for screening genes associated with neurological diseases in humans." (PMID 39634123, 2025). "UNC13B, which is closely related to UNC13A, plays a role in autism spectrum disorders (ASD), epilepsy, and schizophrenia." (PMID 38188011, 2023).
Alzheimer disease (3 papers, 2020 to 2025). A progressive, neurodegenerative disease characterized by loss of function and death of nerve cells in several areas of the brain leading to loss of cognitive function such as memory and language. "Collectively these results demonstrate that mis-processing of STMN2 and UNC13A RNAs is a pathological hallmark of TDP-43-associated Alzheimer’s disease, with amygdala and entorhinal cortex being the most affected areas." (PMID 38175301, 2024). "Findings from multiple GWAS analyses demonstrated that Unc13a is associated with Alzheimer’s disease." (PMID 32392183, 2020). "Collectively this analysis establishes, in a large sample population, that STMN2 and UNC13A transcripts are altered in Alzheimer’s disease patients with advanced Braak stages when the burden of TDP-43 pathology is high." (PMID 38175301, 2024). "Collectively, these results open exciting new avenues to use STMN2 and UNC13A as potential therapeutic targets in a broad range of neurodegenerative conditions with TDP-43 proteinopathy including Alzheimer’s disease." (PMID 38175301, 2024). "We also show, that both STMN2 and UNC13A RNAs are mis-spliced in the amygdala and entorhinal cortex of a substantial fraction of patients with Alzheimer’s disease." (PMID 38175301, 2024). "We demonstrate, for the first time, that accumulation of STMN2 and UNC13A cryptic exons correlates with TDP-43 pathology in Alzheimer’s disease, independently of amyloid-β or tau pathological burden." (PMID 38175301, 2024). "Here, we identify both STMN2 and UNC13A cryptic exons in Alzheimer’s disease patients, that correlate with TDP-43 pathology burden, but not with amyloid-β or tau deposits." (PMID 38175301, 2024). "In addition, splicing alterations in STMN-2 and UNC13A have recently been found in Alzheimer’s disease patients." (PMID 40950074, 2025). "Similarly, our analysis of large RNA-seq datasets from post-mortem tissues also unravels the disruption of STMN2 and UNC13A in Alzheimer’s disease patients." (PMID 38175301, 2024). "We analyzed STMN2 and UNC13A transcripts in bulk RNA-seq from post-mortem brain regions of control and Alzheimer’s disease patients from data available through the Mount Sinai/JJ Peters VA Medical Center Brain Bank (MSBB-AD) and an independent dataset generated at Mayo Clinic." (PMID 38175301, 2024). "Notably, we observed a correlation between the levels of STMN2 and UNC13A cryptic exons detected in the amygdala of Alzheimer’s disease patients (Spearman r = 0.78, p < 0.0001), strengthening the link between detection of cryptic exons and loss of TDP-43 function." (PMID 38175301, 2024). "TDP-43 pathology follows a stereotypic spread as Alzheimer’s disease progress, and we observe that STMN2 and UNC13A are indeed significantly disrupted in temporal cortex of patients with high Braak stages." (PMID 38175301, 2024). "Our study extends on those findings by demonstrating that STMN2 and UNC13A disruption from TDP-43 loss-of-function is detected in large RNA-seq datasets and can distinguish between Alzheimer’s disease patients with and without TDP-43 pathology." (PMID 38175301, 2024). "Our RNA-seq analysis also shows that the STMN2 cryptic exon is enriched in tissues of Alzheimer’s disease; whereas, no significant enrichment of UNC13A cryptic exon was detected." (PMID 38175301, 2024). "Finally, our observations were confirmed by RT-PCR showing the amplification of cryptic exons of both STMN2 and UNC13A transcripts in the amygdala of Alzheimer’s disease patients with TDP-43 pathology, but not in the controls or Alzheimer’s disease patients without TDP-43 pathology." (PMID 38175301, 2024).
Dyskinesia (3 papers, 2018 to 2023). A movement disorder which consists of effects including diminished voluntary movements and the presence of involuntary movements. "Intriguingly, a dominant-negative mutation in UNC13A, which accelerates synaptic vesicle fusion, is also associated with dyskinesia and intellectual disability, reinforcing the importance of tight regulation of the kinetics of neurotransmission." (PMID 30107533, 2018).
Intellectual disability (3 papers, 2018 to 2025). "Collectively, our results suggest UNC13A variants are associated with epileptic encephalopathies and intellectual disability." (PMID 39634123, 2025). "Importantly, our study emphasizes the clinical relevance of rare UNC13A variants in patients presenting with epileptic encephalopathies and intellectual disability, highlighting the potential benefits of incorporating UNC13A screening in future diagnostic workups." (PMID 39634123, 2025).
schizophrenia (3 papers, 2020 to 2025). A major psychotic disorder characterized by abnormalities in the perception or expression of reality. "UNC13B, which is closely related to UNC13A, has shown its significance in autism spectrum disorders (ASD), partial epilepsy, and schizophrenia." (PMID 38188011, 2023).
cognitive decline (2 papers, 2019 to 2024). "Importantly, and in contrast to some of the published literature, 18 31 there is no clear beneficial effect of the putative protective alleles in UNC13A and TMEM106B on cognitive decline, either among those with or without the C9ORF72 repeat expansion." (PMID 37827570, 2024).
microcephaly (2 papers, 2019 to 2023). A congenital or acquired developmental disorder in which the circumference of the head is smaller than normal for the person's age and sex. "Biallelic truncation variants of UNC13A caused severe muscle weakness at birth, microcephaly, hypoplastic corpus callosum, enhanced excitation of cerebral cortex." (PMID 36835142, 2023). "UNC13A-CMS showed severe muscle hypotonia and muscle weakness at birth, and microcephaly and hypoplastic corpus callosum." (PMID 36835142, 2023).
neuroblastoma (2 papers, 2023 to 2025). Neuroblastoma (NB) is the most common solid, extracranial childhood tumor. "The ChIP-seq data revealed that REST binds to the UNC13A promoter in both neuroblastoma and nonneuronal cell lines, and we confirmed this binding pattern in SH-SY5Y cells by ChIP-qPCR analysis." (PMID 40707625, 2025). "To determine if hnRNP L can bind and regulate UNC13A cryptic RNA splicing in a physiological relevant cell type, we performed CLIP of hnRNP L-bound RNAs in human neuroblastoma (M17) cells in which TDP-43 has been down-regulated using siRNA targeting TARDBP (siTARDBP)." (PMID 36930682, 2023).
neuropathy (2 papers, 2021 to 2025). A disorder affecting the nervous system that manifests with pain, tingling, numbness, and/or muscle weakness. "Both the UNC13A and OTOF genes are associated with neuropathy." (PMID 34828297, 2021).
proteinopathies (2 papers, 2024). "In this context, NPTX2 may represent an important therapeutic target for TDP-43 proteinopathies, along with STMN2 and UNC13A." (PMID 38355792, 2024).
Respiratory insufficiency (2 papers, 2019 to 2022). "We aim to confirm the efficacy of lithium carbonate on the time to death or respiratory insufficiency in patients with ALS homozygous for the C-allele at SNP rs12608932 in UNC13A." (PMID 36471413, 2022).
Anxiety (1 paper, 2021). Intense feelings of nervousness, tension, or panic often arise in response to interpersonal stresses. "The reduced level of Unc13a in both the depression-susceptible and insusceptible groups, and the elevated level of Adcy1 in both the anxiety-susceptible and insusceptible groups were recognized when compared with the control group." (PMID 33627638, 2021).
breast carcinoma (1 paper, 2013). "Other coding SNPs that could include causal variants producing synthetic associations (associations of rare with common SNPs of high penetrance) include SNPs in genes INS-IGF2, ZFYVE26, C16orf46, UNC13A, NRIP1 and CCDC91 for breast cancer and SNPs in SNED1 and PASK for prostate cancer." (PMID 23555315, 2013).
corticobasal degeneration (1 paper, 2021). "This revealed a shared signal in the MOBP–RPSA locus between ALS, PSP and corticobasal degeneration (CBD) as well as a shared signal in the UNC13A locus between ALS and FTD (posterior probability, PPH4 > 95%)." (PMID 34873335, 2021).
dementia (1 paper, 2025). Loss of intellectual abilities interfering with an individual's social and occupational functions. "C-allele homozygosity at rs12608932 in UNC13A increased ALS or dementia risk in C9orf72 HRE carriers [hazard ratio 1.81 (1.18–2.78)]." (PMID 40682810, 2025). "Accordingly, models exploring an interaction between C9orf72 HRE status and UNC13A genotype on risk indicated a potential interaction between genotypes for risk of any-cause dementia and ALS or any-cause dementia, but not ALS or FTD alone." (PMID 40682810, 2025).